LDHAP4 (lactate dehydrogenase A pseudogene 4)
Synonyms: formerly LDHAL4
Gene: Transcribed processed pseudogene on chromosome 9 (14,921,337 to 14,922,334, reverse strand). Ensembl gene ENSG00000214110.
Diseases named in the same sentence as LDHAP4 in open-access papers:
LDHAP4 is named in the same sentence as 1 disease in open-access papers, as found by Europe PMC text mining. Sharing a sentence is not in itself a finding about the gene and the disease. The quoted sentences say what the papers report.
tumor (1 paper, 2022). "Compared to HPV negative, patients with HPV positive had significantly higher expressions of oncogene pseudogenes (SDHAP1, SDHAP3, DDX12P, CLUHP3, and RRN3P3), but there was no prominent difference in the expressions of tumor-suppressor pseudogenes (PDIA3P1, LDHAP4, LDHAP7, EEF1A1P6, and EEF1A1P11)." (PMID 36438489, 2022).